BCAR3 (BCAR3 adaptor protein, NSP family member)
Diseases named in the same sentence as BCAR3 in open-access papers (continued):
Sharing a sentence is not in itself a finding about the gene and the disease.
breast carcinoma (continued). "AND-34/BCAR3 induces serine phosphorylation of p130Cas in human breast cancer epithelial cells in an adhesion-dependent manner (unpublished observation)." (PMID 19365570, 2009). "KLF9 over-expressing HEC-1-A cells had increased mRNA expression of BCAR3 and PSAT1, proteins previously implicated in the acquisition of tamoxifen resistance by breast cancer cells." (PMID 18783612, 2008). "For example, CpGs exhibiting higher methylation levels in female cetaceans were linked to genes such as the mTOR-related RRAGA on chromosome 9 (cg04565674, Meta P = 1.0 × 10–159) and the breast cancer-related gene BCAR3 on chromosome 1 (cg06678289, Meta P = 4.6 × 10–36), among others." (PMID 39900928, 2025). "In the context of breast cancer, differential expression patterns of BCAR3 have been observed." (PMID 38730626, 2024). "To investigate whether PTPN14 functions in breast cancer through BCAR3, we used siRNA specifically targeting BCAR3 to downregulate its expression in PTPN14‐KO and control cells." (PMID 39189475, 2024). "Furthermore, BCAR3’s involvement in promoting epithelial–mesenchymal transition is pivotal in breast cancer metastasis and resistance." (PMID 38730626, 2024). "We then assessed the endogenous levels of BCAR3 in a panel of breast cancer cell lines." (PMID 38296970, 2024). "Moreover, BCAR3’s ability to mediate anti-estrogen resistance reveals its potential impact on treatment outcomes in breast cancer, highlighting its importance in the development of resistance to conventional therapies such as tamoxifen." (PMID 38730626, 2024). "BCAR3 mRNA expression is undetectable in normal breast cancer tissue." (PMID 35453754, 2022). "BCAR3 is involved in anti-estrogen resistance in breast cancer cells." (PMID 36109624, 2022). "The role of BCAR3 in cancer is mainly reported in breast cancer." (PMID 34707118, 2021). "Moreover, it was reported that BCAR3 promotes cell motility, focal adhesions, and invasive capacity in breast cancer cells." (PMID 34707118, 2021). "The treatment with CyA restored the abundance of 3 proteins at 1% oxygen to a level similar to that in cells grown at 19% oxygen, selenocysteine-specific elongation factor (EEFSEC), Bardet-Biedl syndrome 12 protein (BBS12) and breast cancer anti-estrogen resistance protein 3 (BCAR3)." (PMID 32183695, 2020). "However, in some researches, overexpression of BCAR3 in breast cancer cells can inhibit cell migration and invasion." (PMID 30563570, 2018). "The function of the BCAR3 (Breast Cancer Antiestrogen Resistance 3) gene is varied." (PMID 30563570, 2018). "It had previously been shown that BCAR3 expression increased proliferation of breast cancer cells." (PMID 29221134, 2017). "However, these breast cancers often become treatment-resistant, and BCAR3 was identified as being involved in the development of anti-estrogen resistance." (PMID 27513743, 2016). "Our data also suggest that BCAR3 may play a favorable role in preventing disease progression in breast cancer patients." (PMID 25499443, 2014). "Therefore, BCAR3 is currently considered to play a role in mediating aggressive breast cancer phenotypes." (PMID 25499443, 2014). "In this study, we investigated whether BCAR3 is a novel antagonist of the canonical transforming growth factor β (TGFβ) pathway, which induces potent migration and invasion responses in breast cancer cells." (PMID 25499443, 2014). "We found BCAR3 to promote an interaction between Smad2/3 and p130Cas, leading to inhibition of Smad activation, Smad-mediated gene transcription and Smad-dependent cell migration and invasion in breast cancer cells." (PMID 25499443, 2014). "However, the authors of a previous report suggested that BCAR3 expression is correlated with favorable outcome in progression-free survival (PFS) in a cohort of ER-positive (ER+) breast cancer patients who had received tamoxifen treatment." (PMID 25499443, 2014).
breast carcinoma (continued). "As such, we investigated whether modulating BCAR3 levels in basal-like breast cancer cells could affect TGFβ-induced cell migration." (PMID 25499443, 2014). "In addition, we found that TGFβ decreased BCAR3 protein expression in multiple breast cancer cell lines." (PMID 25499443, 2014). "As the TGFβ/Smad signaling pathway plays a prominent role in breast cancer progression and tumor metastasis, we investigated whether BCAR3 could regulate TGFβ/Smad signal transduction." (PMID 25499443, 2014). "In addition, we found BCAR3 to inhibit Smad activation, Smad-mediated gene transcription, Smad-dependent cell migration and matrix digestion in breast cancer cells." (PMID 25499443, 2014). "As such, BCAR3 has controversial implications in breast cancer." (PMID 25499443, 2014). "However, our results indicate that BCAR3 acts as a putative suppressor of breast cancer progression by inhibiting the prometastatic TGFβ/Smad signaling pathway in invasive breast tumors." (PMID 25499443, 2014). "Considering that BCAR3 protein levels are elevated in advanced breast cancer cell lines and enhance breast cancer cell motility, we propose that BCAR3 functions in the transition to advanced disease by triggering intracellular signaling events that are essential to the metastatic process." (PMID 23762409, 2013). "Considering that BCAR3 is elevated in advanced breast cancer cell lines and enhances cell motility, we propose that BCAR3 upregulation may be a critical regulator of metastatic progression." (PMID 23762409, 2013). "Future studies will determine whether any of these molecules contribute to the suppression of RhoA by BCAR3 and, in so doing, help to elucidate the mechanism by which BCAR3 affects the balance between Rac1 and RhoA signaling in invasive breast cancer cells." (PMID 23762409, 2013). "Although not mutually exclusive, a second possibility that may account for the BCAR3-dependent Rac1 activity observed in invasive breast cancer cells is that BCAR3 may actively suppress RhoA signaling, leading indirectly to Rac1 activation." (PMID 23762409, 2013). "We hypothesize that BCAR3 expression may become upregulated in breast cancer cells in response to selective pressures present in the tumor microenvironment such as hypoxia or nutrient deprivation." (PMID 23762409, 2013). "However, one study recently identified AND-34/BCAR3 but very little NSP3 or NSP1 protein in human breast cancer lines." (PMID 19365570, 2009). "The BCAR1 and BCAR3 genes both encode components of intracellular signal transduction, but their direct effect on breast cancer cell proliferation is not known." (PMID 15642172, 2005). "Furthermore, BCAR3 expression varies among breast cancer cell lines; it is found in lower amounts in less invasive ER-positive cell lines (MCF-7 and T47D), while more aggressive, metastatic ER-negative cell lines (MDA-MB-231 and BT549) exhibit moderate to high levels." (PMID 38730626, 2024). "Additionally, in Luminal A and B breast cancer subtypes, low BCAR3 expression, alongside BCAR1, correlates with poor prognosis, adverse lymph node status, and diminished response to hormonal therapy, indicating potential as markers for endocrine therapy resistance." (PMID 38730626, 2024). "In addition to the phosphorylation-dependent mechanism investigated here, a previous study showed that TGFβ stimulates proteasomal degradation of BCAR3, and over-expressed BCAR3 and Cas appear to stabilize each other in breast cancer cells, dependent on their mutual binding." (PMID 34169835, 2021). "Additionally, we report a true prognostic value of BCAR3 in human breast cancer." (PMID 25499443, 2014). "Additionally, BCAR3 expression generally correlated with breast cancer subtype." (PMID 25499443, 2014). "Marie-Line Garron and her team provide groundbreaking structural insights into the BCAR3 and HEF1 (NEDD9/Cas-L) complex, revealing its significant role in anti-estrogen resistance and integrin signaling in breast cancer." (PMID 38730626, 2024).
breast carcinoma (continued). "Our study links for the first time SMYD2, BCAR3 and FMNL proteins into a common pathway regulating cellular motility and breast cancer neoplastic cells capacity to metastasize." (PMID 38296970, 2024). "Collectively, these results provide evidence that BCAR3 is a phospho‐substrate for PTPN14 and that the function of PTPN14 in breast cancer anoikis and tumorigenicity involves BCAR3." (PMID 39189475, 2024). "To model metastatic colonization of the lung, we intravenously inoculated highly lung-metastatic prone MDA-MB-231 breast cancer cells with depletion of endogenous SMYD2 and/or BCAR3 complemented with WT or methyl-mutant K334A BCAR3." (PMID 38296970, 2024). "BCAR3 and GDI1 have a role in tumor development and progression and are correlated with resistance to systemic therapy in other tumor types, including breast cancer." (PMID 37940875, 2023). "In invasive, basal-like breast cancer cells, such as MDA-MB-231, SCP2 and SUM-159-PT, BCAR3 antagonizes several of TGFβ’s proinvasive effects, such as cell migration, formation of filopodia-like structures and digestion of gelatin matrix." (PMID 25499443, 2014). "We transiently transfected FLAG-tagged AND-34 (the mouse homologue of BCAR3) into SUM-159PT, which is another breast cancer cell line that expresses low levels of endogenous BCAR3." (PMID 25499443, 2014). "To investigate BCAR3’s clinical implications, we used GOBO to generate Kaplan-Meier survival curves of breast cancer patients derived from published microarray datasets in the NCBI GEO database." (PMID 25499443, 2014). "BCAR3, a member of the novel SH2 domain-containing protein (NSP) family, is overexpressed in breast cancer cell lines representative of more advanced, invasive breast cancers." (PMID 23762409, 2013). "Interest in this protein has focused on the ability of BCAR3 (Breast Cancer Anti-Estrogen Resistance 3), the human homolog of AND-34, to induce anti-estrogen resistance in breast cancer in concert with p130Cas (BCAR1)." (PMID 19365570, 2009). "Consistent with previously characterized tumor-promoting properties of BCAR3, particularly BCAR3 critical role as an activator of p130Cas/BCAR1-dependent cell motility, we observed a pivotal function for K334me1 of BCAR3 in controlling breast cancer migration and metastasis." (PMID 38296970, 2024). "A correlation analysis between the expression of SMYD2 and candidate substrates in metastatic vs non-metastatic breast cancer identified BCAR3 as the strongest positive hit in metastatic breast cancer." (PMID 38296970, 2024). "BCAR3, a member of the novel Src homology 2 (SH2)-containing protein (NSP) family, was first identified in the search for genes involved in the development of estrogen resistance in breast cancer." (PMID 34707118, 2021). "The inhibitory effect of BCAR3 on TGFβ/Smad signaling was observed in all breast cancer cell lines tested, regardless of their molecular phenotype and biological response to TGFβ." (PMID 25499443, 2014). "Notably, we also found similar correlations between low BCAR3 expression and poor prognosis of DMFS and RFS with the Breast Cancer Kaplan-Meier Plotter, which utilizes different but partially overlapping gene profiling datasets compared to those used in GOBO." (PMID 25499443, 2014). "By using a second invasive breast cancer cell line (MDA-MB-231), we also sought to determine whether the impact of BCAR3 signaling on the actin cytoskeleton was consistent across multiple cell lines." (PMID 23762409, 2013). "Together, these data show that RhoA-dependent pathways predominate in invasive breast cancer cells in the absence of BCAR3." (PMID 23762409, 2013). "Despite evidence for BCAR3 as a regulator of invasive breast cancer cell motility and invasion, the role of BCAR3 in other cell types is not widely known." (PMID 23762409, 2013).
breast carcinoma (continued). "To test this hypothesis, we ectopically expressed WT or K334A BCAR3 in non-invasive MCF-7 breast cancer cells characterized by the absence of endogenous BCAR3 expression." (PMID 38296970, 2024). "In the current study, we used MCF-7 breast cancer cell line to determine the effect of EFA-CLA, as potential ligands for peroxisome proliferator-activated receptors (PPARs), on identified in silico PPAR-responsive genes: BCAR3, TCF20, WT1, ZNF621, and THRB (transcript TRβ2)." (PMID 28458685, 2017).
ovarian carcinoma (14 papers, 2017 to 2025). A malignant neoplasm originating from the surface ovarian epithelium. "Breast cancer anti-oestrogen resistance 3 (BCAR3) has been associated with ovarian cancer cell proliferation." (PMID 36759729, 2023). "A 5′fragment of tRNA‐Glu‐CTC (tRF5‐Glu) binds the 3′UTR of BCAR3 regulates its expressions in ovarian cancer." (PMID 35957621, 2022). "In a study of ovarian cancer, tRF5-Glu inhibited cancer cell proliferation by binding to the repressive target gene BCAR3." (PMID 36230476, 2022). "Contrary to tRF-03357, a tRF-5s derived from tRNA-Glu has been elucidated to target the breast cancer anti-estrogen resistance protein 3 (BCAR3) and hence to inhibit the proliferation of ovarian carcinoma cells." (PMID 35574338, 2022). "Studies on BCAR3 in other cancers are quite scarce and the only study in solid tumors showed that BCAR3 inhibition suppresses ovarian cancer cell proliferation." (PMID 34707118, 2021). "As reported, breast cancer anti‐oestrogen resistance 3 (BCAR3) is essential for the development of ovarian cancer." (PMID 33507586, 2021). "The aim of this study was to identify the expression pattern, function and regulation of BCAR3 and tRF5-Glu in ovarian cancer cells." (PMID 29221134, 2017). "We have shown that tRF5-Glu is present in ovarian cancer cells grown in culture and is capable of directly binding a predicted target, the Breast Cancer Anti-Estrogen Resistance gene 3 (BCAR3)." (PMID 29221134, 2017). "In this study, we show decreasing BCAR3 expression and increasing tRF5-Glu inhibits the proliferation of ovarian cancer cells." (PMID 29221134, 2017). "BCAR3 has not previously been studied in ovarian cancer cells and our studies demonstrate that inhibiting BCAR3 expression suppresses ovarian cancer cell proliferation." (PMID 29221134, 2017). "BCAR3 was selected from the genes predicted for regulation due to its expression in the ovarian cancer intraperitoneal xenograft model previously published and available from GEO Profiles (GDS4066:204032)." (PMID 29221134, 2017). "We hypothesized that knocking down BCAR3 expression in ovarian cancer cells would similarly inhibit the proliferation (that is, overall cell number resulting from the balance of cell death and cell division) of ovarian cancer cells." (PMID 29221134, 2017). "In summary, BCAR3 and tRF5-Glu contribute to the complex tumor heterogeneity of ovarian cancer cells and may provide new targets for therapeutic intervention." (PMID 29221134, 2017). "The loss of BCAR3 and subsequent reduction of proliferation had not previously been shown in ovarian cancer cells." (PMID 29221134, 2017). "Similarly, research by Xiannan Meng and team has shed light on microRNA-126-5p’s ability to suppress BCAR3 expression in endometriosis, while Kun Zhou and his team’s discovery of a tRNA fragment, tRF5-Glu, underscores its regulatory influence in ovarian cancer by downregulating BCAR3 mRNA." (PMID 38730626, 2024). "The BCAR3 gene may provide new insights into the mechanism of local estrogen action in endometriosis, and may contribute to the complex tumor heterogeneity of ovarian cancer cells." (PMID 36362120, 2022). "Zhou and colleagues identified that 5’ tsRNA-Glu downregulates BCAR3 via binding to the BCAR3 mRNA 3’ UTR, suppressing ovarian cancer cell proliferation." (PMID 36759729, 2023). "BCAR3 has not been studied in ovarian cancer and little is known regarding its regulation at the mRNA level." (PMID 29221134, 2017).
endometriosis (7 papers, 2020 to 2025). The growth of functional endometrial tissue in anatomic sites outside the uterine body. "Another independent investigation into miRNA associated with endometriosis revealed that a decreased level of miR-126-5p, together with increased BCAR3 expression, promoted the movement and infiltration of endometriosis stromal cells." (PMID 41301870, 2025). "It was also reported that BCAR3 overexpression increased cell migration and invasion in endometriosis." (PMID 35842733, 2022). "Recently, reports have shown that the overexpression of BCAR3 could regulate cytoskeletal rearrangement and improved the cell migration and invasion in endometriosis." (PMID 35842733, 2022). "Downregulation of miR-126-5p via negatively regulating BCAR3 could promote cell migration and invasion in endometriosis." (PMID 32850438, 2020).
breast tumors (5 papers, 2009 to 2022). "However, in primary breast tumors, a relatively low level of BCAR3 expression is associated with poor distant metastasis-free survival and recurrence-free survival." (PMID 35668494, 2022). "We found that loss of BCAR3 expression in primary breast tumors correlates with poor outcomes." (PMID 25499443, 2014). "Having defined BCAR3 as a novel TGFβ/Smad inhibitory molecule, this may account for the relatively low BCAR3 expression levels observed in primary breast tumors associated with worse prognosis and higher levels of disease progression." (PMID 25499443, 2014). "Relatively low levels of BCAR3 expression in primary breast tumors correlate with poor distant metastasis-free survival and relapse-free survival outcomes." (PMID 25499443, 2014). "In the study of tamoxifen in the treatment of metastatic breast cancer, high expression of BCAR3 is related to good progression-free survival, and the expression level of BCAR3 in primary breast tumors is relatively low, which is related to the survival rate of distant metastasis." (PMID 30563570, 2018). "We further investigated whether established disease characteristics can be traced backward to BCAR3 expression levels in primary breast tumors." (PMID 25499443, 2014).
multiple myeloma (4 papers, 2018 to 2024). "It was also found that a high expression level of BCAR3 predicts a better prognosis in multiple myeloma patients." (PMID 34707118, 2021). "As a protective factor for multiple myeloma, high-expressed BCAR3 indicates a favorable prognosis." (PMID 35668494, 2022). "BCAR3 (P = 5.17E−03) is a prognostic factor independent of B2M, MRI, and BMPC in myeloma patients." (PMID 30563570, 2018).
head and neck squamous cell carcinoma (2 papers, 2021 to 2024). A squamous cell carcinoma that arises from any of the following anatomic sites: lip and oral cavity, nasal cavity, paranasal sinuses, pharynx, larynx, and salivary glands. "For instance, in head and neck squamous cell carcinoma (HNSCC), BCAR3 overexpression is linked to enhanced tumor growth, perineural invasion, and worse survival outcomes, proposing it as a valuable prognostic marker." (PMID 38730626, 2024). "The relationship between the clinicopathologic characteristics of head and neck squamous cell carcinoma (HNSCC) patients and BCAR3 was analyzed using the Wilcoxon’s signed-rank test and logistic regression." (PMID 34707118, 2021).
melanoma (2 papers, 2022 to 2024). A malignant, usually aggressive tumor composed of atypical, neoplastic melanocytes. "Recently, the first human trial using phosphopeptide pIRS2 and BCAR3 vaccines in high-risk melanoma demonstrated their immunogenicity and safety." (PMID 35260532, 2022). "In the clinical phase, melanoma patients were inoculated with the BCAR3 peptide vaccine, formulated to trigger an immune response with minimal adverse effects, using an adjuvant and poly-ICLC to boost immunogenicity." (PMID 38730626, 2024). "In-vivo experiments reveal that dendritic cells, laden with the BCAR3 peptide, activate T-cells and suppress tumor growth in a melanoma xenograft model effectively." (PMID 38730626, 2024).